ID1 (inhibitor of DNA binding 1)
Diseases named in the same sentence as ID1 in open-access papers (continued):
Sharing a sentence is not in itself a finding about the gene and the disease.
leukemia (continued). "ID1 has been identified as a potential proto-oncogene in leukemia." (PMID 41146039, 2025). "Our results of reduction of ID1 expression by the inhibition of HIF-1α in transformed leukemia cells supports that ID1 is controlled by HIF-1α, which might be deregulated by either ASXL1 or RUNX1 mutation or coexisted mutant of both genes." (PMID 31640815, 2019). "Therefore, ID1 expression may exert a broad malignant transformation role in other hematologic disorders besides leukemia." (PMID 41146039, 2025). "In addition, ID1 functions as an oncogene in the context of leukemia." (PMID 41146039, 2025). "Silencing ID1 using siRNA in the AML cell line MO7E inhibits cell growth, suggesting that ID1 is required to maintain leukemia cell hyperproliferation." (PMID 41146039, 2025). "MLL-AF9 fusion protein overexpressed fetal liver (FL) cells and BMCs obtained from the Id1−/− mice are used to perform serial replanting assays to mimic infant and postnatal MLL-AF9-driven leukemia, respectively." (PMID 41146039, 2025). "The transcription factor, Inhibitor of DNA-binding-1 (ID1), plays a crucial role in the growth and advancement of various cancer forms, such as leukemia." (PMID 39048945, 2024). "ID1 expression is increased in leukemic cells from AML patients with t translocations, and AML1-ETO regulates the ID1 promoter, suggesting a role for ID1 in AML1-ETO leukemia." (PMID 35990659, 2022). "Ablation of Id1 in AML1-ETO transduced murine fetal liver cells delays the onset and development of leukemia by roughly 130 days after transplantation in vivo." (PMID 35990659, 2022). "Interestingly, loss of Id1 accelerated the progression of MLL-AF9-induced leukemia of BMCs, suggesting that Id1 is not required for MLL-AF9-induced leukemia of BMCs, and that leukemogenesis may differ significantly for FL and BM HSPCs." (PMID 35990659, 2022). "A recent study sheds light on how ID1 regulates leukemia progression in a noncell-autonomous manner since ID1 is widely expressed in various cells in the BM microenvironment." (PMID 41146039, 2025). "Data presented here showed that either ASXL1-R693X or RUNX1-R135T mutant alone did not have much effect on leukemia cells; however, cooperative mutations led to the enhancement of HIF-1α recruitments to the promoter region of the ID1 gene." (PMID 31640815, 2019). "However, secondary recipients did not develop leukemia, suggesting that prevention of differentiation by Id1 does not induce transformation." (PMID 41303422, 2025). "Given that ID1 promotes AKT1 phosphorylation through its C-terminal region without disrupting its interaction with bHLH, combined targeting of ID1 and AKT1 might be a promising therapeutic strategy for leukemia." (PMID 41146039, 2025). "Thus, cytogenetically normal (CN) young patients with high ID1 expression have lower complete remission (CR) rates, and worse OS and DFS, suggesting that ID1-negative patients should be classified as unfavorable-risk leukemia." (PMID 41146039, 2025).
osteosarcoma (11 papers, 2009 to 2026). A usually aggressive malignant bone-forming mesenchymal neoplasm, predominantly affecting adolescents and young adults. "In osteosarcoma and cervical cancer patients, high Id-1 expression is correlated with more aggressive behavior as well as much shorter overall survival." (PMID 29233161, 2017). "PI3K/Akt signaling is a downstream component of Id1 and promotes osteosarcoma progression." (PMID 28122577, 2017). "Accordingly, the PI3K inhibitor LY294002 decreases Id1-induced osteosarcoma tumor growth." (PMID 28122577, 2017). "For example, it deubiquitinates and stabilizes ID1, ID2 and ID3 proteins to enhance the proliferation of osteosarcoma." (PMID 38366146, 2024). "By the way, CD117, IBSP (Stro-1), ID1, SOX9, CD24, CD44 and THBS-1 were also reported to affect osteosarcoma growth and stemness." (PMID 34828292, 2021).
neuroblastoma (10 papers, 2016 to 2025). Neuroblastoma (NB) is the most common solid, extracranial childhood tumor. "STAT3 inhibition decreased the upregulation of ID1 levels caused by heparin-binding epidermal growth factor (HB-EGF) in neuroblastoma cells." (PMID 38183094, 2024). "Remarkably however, the activity of BMP signaling in metastatic neuroblastoma cells in the bone marrow was much higher than in primary tumors, with an 8-fold higher expression of ID1—reaching levels comparable to CHP-134 cells in vitro." (PMID 40021625, 2025). "Although autophagy has been proposed as a mechanism of Id1 degradation in neuroblastoma cells, our data indicate that the autophagy inhibitor CQ does not affect the trametinib-mediated Id1 downregulation in KRAS-mutant LUAD cells." (PMID 38643157, 2024). "We found that ionomycin/EB1089 can activate CaMKII to phosphorylate Beclin 1/Id-1, which further induces the differentiation of neuroblastoma cells." (PMID 29079782, 2017). "In neuroblastoma cells, ID1 is downregulated in a hypoxic situation, but it is upregulated by HIF-1α in the absence of hypoxia-induced ATF-3." (PMID 27127787, 2016). "In response to calcium stimulation, CaMKII (Calcium/calmodulin-dependent protein kinase II) mediates S90 phosphorylation, which facilitates K63-ubiquitination-dependent autophagic degradation of Id1/2 (inhibitor of differentiation-1/2) promoting neuroblastoma differentiation." (PMID 30370269, 2018). "To verify this statement, we knocked down Id-1 or Id-2 with shRNA in neuroblastoma cells." (PMID 29079782, 2017). "ID1 and ID2 correlated positively with SNV signature SBS18, which indicates co-occurrence of DNA damage by ROS and replication slippage in MYCN-amplified neuroblastomas." (PMID 37868040, 2023). "ID1 and ID2, both characterized by 1 bp insertions and deletions at long thymine homopolymers attributed to replication slippage and found in most cancer entities, were also recurrently identified in neuroblastoma genomes." (PMID 37868040, 2023). "In the human neuroblastoma cell line, SK-N-MC, it was found that fibroblast growth factor-2 (FGF-2) can induce Id1 expression at both the mRNA and protein levels; the inhibition of Id1 expression results in an accumulation of FGF-2-treated cells at the G2/M stage and postpones cell death." (PMID 32708313, 2020).
acute myeloid leukemia (9 papers, 2017 to 2025). Acute myeloid leukemia (AML) is a group of neoplasms arising from precursor cells committed to the myeloid cell-line differentiation. "Overexpressed Id1 or Id3 are able to immortalize growth factor-dependent hematopoietic progenitors resulting in cells with an acute myeloid leukemia (AML)-like morphology and decreased p15INK, p16INK4, p19ARF and p21Cip1 in vitro." (PMID 28122577, 2017). "In acute myeloid leukemia Id1 has been shown to be a target of the oncogenic tyrosine kinases FLT3-ITD and BCR-ABL, which results in protection of the cells against TRAIL-induced apoptosis." (PMID 28122577, 2017). "Our present work identified ID1, inhibitor of DNA binding 1, HLH protein, was significantly down-regulated in both MDA-MB-231BR AKT1_KO cell lines and in line with this, the regulation of AKT-signaling by affecting ID1 was reported earlier in acute myeloid leukemia." (PMID 37483521, 2023). "Noticeably, Id1 expression is not an independent prognostic factor in acute myeloid leukaemia with normal karyotype when CEBPA mutations were included in the analysis." (PMID 32410828, 2020). "Compared with healthy controls, elevated ID1 expression has been observed in BMCs of acute myeloid leukemia (AML) and myelodysplastic syndrome (MDS) patients." (PMID 41146039, 2025). "It has been reported that ID1 expression could be induced by 5‐aza in low ID1‐expressing acute myeloid leukemia (AML) cells, which resulted in an increase in cell apoptosis; however, this induction could not be explained by direct demethylation of the ID1 gene promoter." (PMID 37964494, 2024). "Our previous study has revealed ID1 expression and its prognostic value in acute myeloid leukemia (AML)." (PMID 29190891, 2017). "Overexpression of Id1 is seen in acute myeloid leukemia (AML) patients." (PMID 32410828, 2020).
esophageal squamous cell carcinoma (8 papers, 2007 to 2025). Esophageal squamous cell carcinoma (ESCC) is a type of esophageal carcinoma (EC) that can affect any part of the esophagus, but is usually located in the upper or middle third. "Inhibitor of DNA binding 1 (ID1) is a key transcriptional regulator involved in the development of various cancers, including esophageal squamous cell carcinoma (ESCC)." (PMID 40652518, 2025). "The results above suggested that TCF3 affected the stemness of esophageal squamous cell carcinoma by regulating ID1." (PMID 37607071, 2023). "Id-1 has been shown to be overexpressed in oesophageal squamous cell carcinoma (ESCC)." (PMID 18000500, 2007). "Recently, Id-1 has been shown to be upregulated in oesophageal squamous cell carcinoma (ESCC)." (PMID 18000500, 2007).
small cell lung carcinoma (8 papers, 2010 to 2023). Small cell lung cancer (SCLC) is a highly aggressive malignant neoplasm, accounting for 10-15% of lung cancer cases, characterized byrapid growth, and early metastasis. "Neuron-specific enolase promoted stem cell-like characteristics of small cell lung cancer cells by activating the BMP2/Smad/ID1 pathway." (PMID 37416767, 2023). "In small cell lung cancer, it has been reported that the high expression of ID1 can significantly inhibit the apoptosis of tumor cells." (PMID 33992097, 2021). "Numerous studies indicated the important role of Id1 in angiogenesis, for example, in small cell lung cancer, suppressed expression of Id1 and Id3 was accompanied by decreased angiogenesis." (PMID 32410828, 2020). "Suppressing both Id1 and Id3 expression was accompanied by decreased angiogenesis and increased apoptosis and greatly reduced the average size of small cell lung cancer in nude mice." (PMID 32410828, 2020). "Silencing Id3 alone in small cell lung carcinoma can also reduce proliferation in spite of persistent Id1 expression." (PMID 23342268, 2012).
squamous cell carcinoma (8 papers, 2010 to 2021). A carcinoma arising from squamous epithelial cells. "For histology, ID1 mRNA expression level was significantly associated with unfavorable OS in adenocarcinoma and squamous cell carcinoma." (PMID 32003423, 2020). "Our study pointed out that EBV and high-risk HPVs are co-present in 34% of our samples; more significantly, we noted that the co-incidence of these viruses is associated with poorly differentiated squamous cell carcinomas, which is accompanied with Id-1 overexpression." (PMID 30035100, 2018). "Moreover, we found that the co-expression of LMP1 and E6 (of EBV and HPV, respectively) is associated with diffuse and strong Id-1 overexpression in all invasive squamous cell carcinomas including high-grade carcinomas (p = 0.001)." (PMID 30035100, 2018). "With regard to NSCLC, other authors have also observed that Id1 is expressed in a nuclear pattern in the majority of squamous cell carcinomas (70%) and non-squamous cell carcinomas (50%) of the lung." (PMID 23311395, 2013). "ID proteins are overexpressed and ID1 may serve as an independent prognostic factor to predict survival time of human oral squamous cell carcinomas but also in other squamous cell carcinoma entities." (PMID 33477984, 2021). "Similarly, among the 9 matched squamous cell carcinomas evaluated elevated, Id1 expression was found to be elevated in tumor specimens versus normal lung in 5 cases with no notable association with tumor stage at the time of diagnosis." (PMID 20414347, 2010).
endometriosis (7 papers, 2014 to 2024). The growth of functional endometrial tissue in anatomic sites outside the uterine body. "As the TATA box lacking genes are intensively dependent to their CAT box region, the role of NF-Y protein in ID2 gene regulation and epigenetic in endometriosis patients is more significant than its binding to the ID1 and ID3 genes." (PMID 30876429, 2019). "Herein, we investigate the expression of VEGF-A in the peritoneal mesothelium and determine if it is regulated by TGF-β1 through an ID1 pathway in women with endometriosis." (PMID 26577912, 2015). "In conclusion, this study demonstrates a functional role for ID1 in the peritoneum of women with endometriosis through the overexpression of VEGF-A to potentially increase neoangiogenesis at sites of endometriosis lesions." (PMID 26577912, 2015). "Our data supports role for ID1 in the pathophysiology of endometriosis, as an effector of TGFβ1 dependent upregulation of VEGF-A, and highlights a novel potential therapeutic target." (PMID 26577912, 2015). "A study showed that Id1 has been implicated in VEGF-A regulation during tumor angiogenesis and peritoneal expression of VEGF-A is regulated by TGF-β1 through the ID1 pathway in women with endometriosis." (PMID 30949224, 2019). "ID1 expression was increased in the peritoneum of women with endometriosis (P < 0.05)." (PMID 26577912, 2015). "Herein, we determined whether peritoneal expression of VEGF-A is regulated by TGF-β1 through the ID1 pathway in women with endometriosis." (PMID 26577912, 2015). "The binding level of NF-Y protein complex to the promoter regions of ID1, ID2, and ID3 genes was displayed through ChIP-Real-Time-PCR and according to the results; it was considerably increased in eutopic group of endometriosis patients in proliferative phase." (PMID 30876429, 2019). "ID1 was increased in peritoneum from women with endometriosis and TGF-β1 increased concentrations of ID1 mRNA (P < 0.05) in mesothelial cells." (PMID 26577912, 2015). "Furthermore, the incorporation of NF-Y complex on CCAAT box region of ID1, ID2, and ID3 promoters was highly enhanced in endometriosis patients." (PMID 30876429, 2019). "We hypothesized that the peritoneal mesothelium is a source of VEGF-A in endometriosis and that TGF-β1 regulates the expression of VEGF-A in the peritoneal mesothelial cell through the ID1 pathway, supporting lesion vascularization." (PMID 26577912, 2015). "However, given that SMAD4 enrichment was decreased at the ID1 and ID3 promoter regions, and this corresponds with decreased ID gene expression, it was likely that BMP signaling pathways also impair SMAD1/5/4 binding activities in the stromal cells from individuals with endometriosis." (PMID 38402336, 2024). "In addition, we show that ID1 mRNA expression is increased in peritoneal biopsies from women with endometriosis compared to women without disease and that ID1 expression is increased in peritoneal mesothelial cells on exposure to physiological concentrations of TGF-β1." (PMID 26577912, 2015). "Similar to BMP2, the ID1 and ID3 genes were progressively increased over the time course treatment in the samples derived from donors without endometriosis while they were conversely downregulated in the endometriosis cohort." (PMID 38402336, 2024).
esophageal cancer (7 papers, 2010 to 2025). A primary or metastatic malignant neoplasm involving the esophagus. "Both the PI3K inhibitor LY294002 and the NF-κB inhibitor Bay 11-7082 increased the sensitivity of Id1-overexpressing esophageal cancer cells to TNF-α-induced apoptosis." (PMID 41303422, 2025). "Li showed that in esophageal cancer cells, stable ectopic expression of Id-1 induced the expression of pAKT, glycogen synthase kinase 3β, and inhibitor of kappa B, as well as increased nuclear translocation of NF-κB subunit p65 and NF-κB binding activity." (PMID 41303422, 2025). "For instance, in esophageal cancer, overexpression of ID1 enhanced cell resistance to etoposide-induced apoptosis, and knockdown of ID1 increased the percentage of apoptotic esophageal cancer cells." (PMID 29169374, 2017). "In addition, Id1-overexpressing esophageal cancer xenografts were characterized by IGF2-dependent metastatic spread." (PMID 36672737, 2023). "Notably, ID1 is involved in chemotherapy and radiotherapy resistance in human cancers including pancreatic, breast, lung, colorectal, and esophageal cancers." (PMID 29169374, 2017). "Similarly, IGF2 expression was associated with Id1 and activated AKT in esophageal cancer tissues." (PMID 36672737, 2023). "For instance, in esophageal cancer models, IGF2 secreted by Id1-overexpressing cells induced CAFs to produce and secrete vascular endothelial growth factor (VEGF) by inhibiting miR-29c." (PMID 36672737, 2023). "Another study identified a detailed E2F transcription factor 1 (E2F1)‐dependent mechanism by which inhibitor of DNA binding 1 (Id1) increases the expression of TS and insulin‐like growth factor 2 (IGF2) to promote esophageal cancer chemoresistance." (PMID 34766149, 2021).
liver cancer (7 papers, 2013 to 2024). An epithelial or non-epithelial malignant neoplasm that arises from the liver. "BMP-9 has been shown to activate Smad-dependent pathways through Smad1/5/8 to cause ID1 up-regulation and growth promotion in HepG2 liver cancer cells." (PMID 27650540, 2016). "Researchers have also found that BMP9 stimulation of liver cancer cells can trigger the phosphorylation of Smad1/5/8 and upregulation of inhibitor of differentiation-1 protein(ID1)." (PMID 39619441, 2024). "Studies have shown that BMP9 and ID1 are overexpressed in malignant liver tumor tissues and play important roles in the angiogenesis of liver cancer tissues." (PMID 39619441, 2024). "As ID1 was identified as a potential downstream effector molecule of KIS via analysis of KIS siRNA-transfected liver cancer cells in the GSE121733 dataset, the ID1 and its related β-catenin pathway was further investigated in the present study." (PMID 39052126, 2024). "Research on the liver cancer signaling pathway has revealed that bone morphogenetic protein 9 (BMP9) and inhibitor of DNA binding 1 (ID1) can activate the expression of HIF-1α and VEGFA, which affects the angiogenesis of liver cancer lesions." (PMID 39619441, 2024). "In the liver cancer cell line HepG2, BMP9 triggers Smad1,5,8 phosphorylation and inhibitor of DNA binding 1 (Id1) expression up- regulation." (PMID 23936038, 2013). "However, the role of the AKT/mTOR/STAT3/ID1 axis in liver cancer remains unexplored, and the effects of therapeutics targeting the AKT/mTOR/STAT3/ID1 signaling pathway remain unknown." (PMID 38183094, 2024).